STAT3 (signal transducer and activator of transcription 3)
Diseases named in the same sentence as STAT3 in open-access papers (continued):
Sharing a sentence is not in itself a finding about the gene and the disease.
tumor (continued). "In this research, it was found that Notch4 activated STAT3 and that this pathway has induced epithelial-to-mesenchymal transition (EMT) in tamoxifen-resistant tumor cells." (PMID 32605277, 2020). "IL-17A, predominantly secreted from Th17 cells, inhibited STAT3-dependent CXCR3 expression on CD8+ T cells, leading to decreased CD8+ T cell migration to tumor tissues." (PMID 32503584, 2020). "In GC, tumor-derived granulocyte-macrophage colony-stimulating factor (GM-CSF) activates neutrophils and induces PD-L1 expression on neutrophils via the JAK/STAT3 signaling pathway." (PMID 32944395, 2020). "More importantly, HNC0014 treatment significantly delayed tumor growth in a syngeneic mouse HNSCC model, elicited an antitumor immune profile, and reduced the total c-Met, STAT3, and their phosphorylated forms, PD-L1 and CD44, contents in serum exosomes." (PMID 33327484, 2020). "STAT3 controls many MDSC-released mediators (cytokines, growth factors, enzymes) that promotes pro-tumor effects." (PMID 32133298, 2020). "For instance, curcumin suppresses tumor growth by inhibiting tumor-promoting pathways, such as the NF-kB, Wnt/β-catenin, Notch signaling, as well as the JAK/STAT3 and MAPK pathways." (PMID 33092261, 2020). "Activation of the IL-6/STAT3 pathway induces the expression of IGF-1/IGF-1R, thereby initiating the IGF-1/IGF-1R autocrine and paracrine loop within tumor bulk to induce stemness-related gene expression." (PMID 33511137, 2020). "STAT3 can be activated by various cytokines, such as IL-6, CXCL-5, and COX2/PGE2, from PCa cells and the tumor microenvironment." (PMID 32546700, 2020). "FAP positive CAF secrete high levels of CCL2 which in turn addresses the CCL2 receptor (CCR2) on circulating MDSC, activating immunosuppressive STAT3 signaling and leading to an enrichment of MDSC in tumor tissues." (PMID 32899119, 2020). "(E) Immuno-blots showing the levels of phospho-STAT3, STAT3 and ACTIN between the sorted Neu tumor sub-populations." (PMID 32840210, 2020). "Previous studies showed that the IL-6/JAK-STAT3 pathway is abnormally hyperactivated in multiple tumor types and elevated expression of IL‐6 can stimulate hyperactivation of JAK/STAT3 signaling which usually leads to an unfavorable clinical outcome 43-45." (PMID 32742470, 2020). "STAT3 is part of the IL- 6/JAK/STAT3 pathway, which is hyperactive in many cancers and is known to suppress the anti-tumor immune response." (PMID 32552875, 2020). "CAFs from hepatic cancer attract monocytes to the tumor microenvironment by CXCL12 and induce their differentiation into MDSCs through IL-6-mediated STAT3 activation." (PMID 32793192, 2020). "Most importantly, IL-6 leads to the activation of STAT3 and overexpression of downstream tumor-suppressor genes in HNSCC, which subsequently propels the reinforcement of tumor cell expansion and migration." (PMID 33203092, 2020). "Western blot analysis indicated that both STAT3 and p-STAT3 (Tyr705) protein levels were increased in human ECSS samples compared with adjacent non-tumor tissue samples." (PMID 33390934, 2020). "Different transcription factors, such as STAT3 or nuclear factor-κB (NF-κB), can amplify the immune cell population or they can be manipulated by the TME to allow for tumor proliferation and circumvention of apoptosis." (PMID 33138184, 2020). "IL-6, secreted by the myeloid cells, activates STAT3, which then upregulates cyclins D1, D2, and B as well as MYC to promote tumor cell proliferation." (PMID 33143283, 2020). "We also detected STAT3 and KRAS being upregulated in the tumor and metastatic tissue of a subset of patients." (PMID 32345963, 2020). "Using total protein from HCC827 xenograft tumour tissues, we found that Afatinib inhibited the phosphorylation of JAK1,2, STAT3, and FAK, the protein expression of LYVE-1, VEGFR2, VEGFR3, VEGFC, VEGFA, and CCR7." (PMID 31892990, 2020).
tumor (continued). "IL-6 then activates the signal transducer and activator of transcription 3 (STAT3) pathway in immune cells, stromal cells, and tumor cells, which supports the overall immune escape of cancer cells." (PMID 33228245, 2020). "The same study has shown the increment of tumor sensitivity by an intensification of p-ERK and reduction of p-STAT3 signaling." (PMID 33379302, 2020). "All these results implicate GM-CSF and STAT3 as critical drivers of liver MDSC IDO/PD-L1 expression and potential mechanistic targets to enhance intrahepatic anti-tumor immunity." (PMID 33322216, 2020). "Neutrophils can be recruited by CXCL8-secreting tumor cells and, in turn, modulate tumor growth by secreting the proliferation-inducing ligand APRIL and up-regulating the NF-kB, STAT3, and p38 pathways via the Toll-like receptor 9 signal." (PMID 32296632, 2020). "In another study it was found that IL-22—whose expression by T cells was increased in TNBC tumor tissues compared to para-tumor and normal areas—induced paclitaxel resistance in TNBC cell lines, accompanied by elevated JAK/STAT3 activation." (PMID 33585241, 2020). "Another study demonstrated that herbal acidic polysaccharide IAPS-2 inhibits the phosphorylation of STAT3 and enhances STAT1 phosphorylation in TAMs from S180 tumor tissues (a syngeneic sarcoma) promoting macrophage polarization toward the M1-like phenotype." (PMID 32486098, 2020). "In vivo, AT-I significantly inhibited tumour growth and reduced the expression of HK2, phosphorylated JAK2 and STAT3." (PMID 32273843, 2020). "Two studies showed that fedratinib in combination with erlotinib (EGFR tyrosine kinase inhibitor) decreased STAT3 activation and increased apoptosis in erlotinib-resistant NSCLC cells and inhibited tumor growth in in vivo murine models." (PMID 33521321, 2020). "In a tumor vaccination approach, we found Stat3∆/∆ CD103+ cDC1s restrained mammary gland tumor growth and increased mouse survival more effectively than STAT3-sufficient CD103+ cDC1s." (PMID 31947933, 2020). "In addition to its central role as a pyruvate enzyme at cytoplasm, PKM2 may also translocate into the nucleus to function as a protein kinase and interact with many tumor-associated genes to accelerate carcinogenesis, including HIF-1α, Oct-4, STAT3 and beta-catenin 26,37-39." (PMID 32308748, 2020). "Shikonin has been demonstrated to target the SH2 domain of STAT3 resulting in the suppression of IL-17-induced vascular endothelial growth factor (VEGF) expression, sensitization to gefitinib and the induction of tumour cell apoptosis." (PMID 32731620, 2020). "Additional signaling pathways involved in the anti-tumor immune response were also impaired as STAT1 and STAT3 were also significantly downregulated." (PMID 33034643, 2020). "It is interesting to note that STAT3 regulates VEGF expression, directly binding to the VEGF promoter and strengthening expression of VEGF and tumor angiogenesis." (PMID 31949487, 2020). "STAT3 synergizes with STAT6 in macrophages to promote cathepsin secretion and tumor invasion through the IRE1α pathway." (PMID 32793192, 2020). "OSM promotes epithelial to mesenchymal transition (EMT) of cancer stem cell (CSC) properties by activating Stat3/TGF-β/SMAD3 signaling, and therefore, promotes tumor metastasis and tumor recurrence." (PMID 33216732, 2020). "Research on the detailed mechanisms of this process showed that CCc proliferation occurs through an IL-6/JAK2/STAT3-dependent mechanism and VEGF-induced tumor angiogenesis." (PMID 32429087, 2020). "Un-phosphorylated STAT3 (U-STAT3) can be found both in the cytoplasm and in the nucleus and, similar to activated STAT3 (pSTAT3), it may form dimers and display activity as a transcription factor, a phenomenon that can be observed in normal somatic cells as well as in tumor cells." (PMID 32488850, 2020).
tumor (continued). "Of note, it has been shown that long noncoding RNA TSLNC8 blocks tumor growth by reducing the interaction between TKT and STAT3 and inhibiting IL-6/STAT3 signaling pathway." (PMID 31949131, 2020). "When promoting tumor growth, TNFα activates NF-κB and p38/MAPK pathways which stimulate signal transducer and activator of transcription 3 (STAT3), a known transcription factor classified as an oncogene." (PMID 32391269, 2020). "Persistent activation of STAT3/STAT5 often promotes chronic inflammation leading to transformation of healthy cells into malignant cells, while STAT1 suppress tumor growth." (PMID 32991625, 2020). "Western blot results revealed that the levels of p‐STAT3 (Tyr705), vimentin, MMP‐13, and MMP‐3 decreased in the tumor tissues grown from HeLa cells in the RES pretreatment and treatment groups, compared with those in the respective control groups." (PMID 33040485, 2020). "Resveratrol, Lipoxin, Glucosides of Paeony have also inhibited Bregs through STAT3 and/or ERK inactivation leading to a reduction in IL-10 and TGF-β levels thus exerting an anti-tumour effect." (PMID 31901949, 2020). "Both IGF-1R inhibitor and mTOR inhibitor treatment significantly reduced the tumor growth in ES xenografts through inhibition of IGF-1R/PI3K/AKT/mTOR, and other signaling pathways, including MEK1/2, JAK/STAT3, TGF-β, and G-protein coupled receptors." (PMID 32754598, 2020). "Re-sensitizes radioresistant cells to radiotherapy by inhibition of STAT3; when combined with ERK1/2 inhibitors, it remarkably eliminates resistant cells and inhibits tumor regrowth." (PMID 32872659, 2020). "Moreover, SD-36 treatment can cause a profound and long-lasting suppression of tumor in mouse models of leukemia and lymphoma, suggesting that PROTAC-based strategy may be a promising and reliable avenue for searching small molecule inhibitors against STAT3." (PMID 32972405, 2020). "The tumor tissues were then lysed for western blotting, which demonstrated 20(S)-25-OCH3-PPD targets in the STAT-3 signaling pathway." (PMID 32425780, 2020). "Based on this finding, we examined the correlation between p-STAT3 and HIF-1α protein expression in tumor samples." (PMID 31942180, 2020). "Similar to the effect of DCZ0858 on c-Myc, silenced STAT3 also downregulated c-Myc expression at the transcription level and thus partially exhibited the DCZ0858-mediated tumor suppression phenotype." (PMID 32296013, 2020). "Another, although controversial tumour suppressor is the signal transducer and activator of transcription (STAT) family protein member STAT3." (PMID 33256730, 2020). "Via phosphorylation of STAT3, CD24 induces NANOG, a key factor for self-renewal in embryonic stem cells and during tumor development, thus enabling HCC cell self-renewal." (PMID 32183251, 2020). "Some of the critical TFs involved in carcinogenesis are inflammatory TFs such as NF-kB, STAT3, and AP1, which regulate genes for tumor initiation and progression." (PMID 32824207, 2020). "In many solid tumors and hematologic malignancies, signal transducer and activator of transcription 3 (STAT3) is constitutively activated, thereby driving the malignant behavior of tumor cells." (PMID 33374980, 2020). "Upon TLR9 activation, STAT3 phosphorylation at Tyr705 was increased, which led to PD-L1 expression upregulation in HCC cells, suggesting that tumor cells can be directly affected by TLR9 ligation to escape immune attack." (PMID 32483468, 2020). "Over-activation of tyrosine kinase (JAK) and related transcription factors STAT3 and STAT5 in the cytoplasm of tumor cells can be found in most of the malignant tumors." (PMID 33117713, 2020). "For example, a positive FFL IL-6/JAK/Stat3, in which IL-6 activates JAK and STAT3 was involved in tumor proliferation, tumor microenvironment shaping, and metastasis." (PMID 31537905, 2020).
tumor (continued). "It was interesting to detect differences in CD44, ALDH1 protein and STAT3 gene expression between the UWG02CTC and UWG02ASC, which probably reflects the different pathways of tumour cell dissemination." (PMID 31953491, 2020). "Inhibition of STAT3 restored the oncogenic effect of RAI14, and RAI14 silencing restrained tumor growth and the protein level of Ki67 in vivo." (PMID 32957082, 2020). "Interestingly, some recent studies suggest previously unknown functions of STAT3 in tumor immunity." (PMID 32972405, 2020). "In vivo, Phosphatase and tensin homolog (PTEN)-null senescent cells secrete cytokines through the Jak2/Stat3 pathway; promote the infiltration of immunostimulatory CD8+ T cells, NK cells, and B cells; and decrease the tumor size and invasion capacity." (PMID 32028565, 2020). "An overexpression with constitutively active STAT3 construct in HNSCC cells showed Cyclin D1 overexpression, increased proliferation in vitro and higher rates of in vivo tumor growth in mice." (PMID 33344262, 2020). "Taken together, our data imply that IL-10-mediated signaling via STAT3 elicits immunosuppressive responses in CD103+ cDC1s, thereby reducing CD103+ cDC1-mediated anti-tumor immunity." (PMID 31947933, 2020). "Tumor-produced IL-6 and PGE2 led to increased levels of activated Signal Transducer and Activator of Transcription 3 (STAT3) and decreased levels of activated STAT1 and STAT6, respectively." (PMID 32656079, 2020). "We demonstrate that CircRNA_ACAP2 functions as a tumor suppressor gene in HNSCC and that its function is regulated via the miR-21-5p/STAT3 signaling axis." (PMID 33363013, 2020). "The regulation of the proliferation, invasion and metastasis of tumor cells allows for the interaction of phosphorylated FAK and SRC with the STAT3 signaling pathway." (PMID 33240810, 2020). "STAT3 is a key factor downstream of EGFR signalling, and EGFR-mediated STAT3 activation is essential for skin carcinogenesis in mice." (PMID 32899142, 2020). "Hence, STAT3 activation in tumor cells may promote tumor progression." (PMID 32127943, 2020). "The survival benefits of STAT3 inhibition have been shown in a GL261 model, where the expression of cytokines promoting tumour growth, such as IL‐10 and IL‐6, was blocked." (PMID 32567735, 2020). "Histopathology imaging features of anatomic structures show that higher expression of STAT3, AHR, and CCR2 modules distinguishes between samples derived from the cellular tumor compared with those from leading edge and infiltrating tumor regions." (PMID 32383980, 2020). "Following the binding of lactate in the TME to MCT1, intracellular signaling pathways are activated that alter the expression of downstream effector molecules and allow tumor cells to become drug-resistant, via the AKT/mTOR, NF-κB and STAT3 signaling pathways." (PMID 33153193, 2020). "Signal transducer and activator of transcription-3 (STAT3) gene is an oncogene and is overexpressed in many tumor types." (PMID 33344242, 2020). "Phosphorylated STAT3 and STAT6 together cooperated to increase cathepsin expression in TAMs resulting in the enhanced tumor invasion in vivo." (PMID 32486098, 2020). "Functional experiments showed that DCZ0858 had a tumor-suppressive effect on DLBCL cells, mainly through cell proliferation inhibition, apoptosis induction, and cell cycle arrest via the JAK2/STAT3-signaling pathway." (PMID 32296013, 2020). "STAT3, a member of the STAT protein family, is an important regulator in tumor cells and plays a critical role in inflammation and tumorigenesis by regulating cell metabolism." (PMID 32377171, 2020). "We previously demonstrated that combined targeting of the STAT3 and SRC family pathways significantly increased anti-tumor activity." (PMID 32927828, 2020).
tumor (continued). "Silencing of the signal transducer and activator of transcription-3 (STAT3), an important mediator for the subtype of highly aggressive mesenchymal GBM, by a novel aptamer-siRNA chimera (Gint4.T) inhibits tumor growth and angiogenesis in a mouse model." (PMID 32188434, 2020). "PXA3-FKHR interacted with STAT3 to reduce the expression of MHC and generate immunoinhibitory secreted factors such as IL-10 in tumor cells." (PMID 32872659, 2020). "Increased HB-EGF secretion in HLMFs, which upregulate α-SMA, markedly increases tumor formation of CC cells and tumor invasion in vivo by EGFR activation-mediated upregulation of PECAM-1 and activation of STAT3/ERK." (PMID 32708604, 2020). "Next, we explored changes in STAT3, AKT, and ERK pathways by western blot analysis in tumor tissues." (PMID 32814829, 2020). "Highly relevant nodes in the modules, including STAT3, SLC11A1, and ITGAM, have been reported to promote tumor proliferation, angiogenesis, migration, and invasiveness." (PMID 32211315, 2020). "Metformin also selectively acts against CSCs by targeting EMT, blocking the IL-6/STAT3 axis or decreasing EMT transcriptional factors, and by increasing tumor sensitivity against other current therapies; therefore, it has been included in clinical trials." (PMID 33059744, 2020). "Human MSCs treated with TGF-β1 can be recruited to the tumor site and induced to express markers of CAFs in vitro by upregulation of JAK/STAT3 signaling." (PMID 33322749, 2020). "In this study, DDP also delayed tumour growth in LC mice with PCBS syndrome and downregulated the STAT3, p-STAT3, and cyclin D1 protein expression levels to some extent." (PMID 32382281, 2020). "The expression of the MUC1gene mediates tumor invasion and it is also controlled by STAT-3.Thus, STAT-3 tumor invasion can be induced through several mechanisms." (PMID 32167126, 2020). "MSCs promotes tumour growth by increasing the number of cancer stem cells through bone morphogenetic protein signalling and WNT, TGF‐β, IL‐6/JAK2/STAT3 signalling pathways." (PMID 32588948, 2020). "Compelling evidence suggests that the Signal Transducer and Activator of Transcription 3 STAT3 is constitutively activated in many cancers, promoting tumor growth and metastasis." (PMID 33255335, 2020). "Given the pivotal role of CDK7 in regulating the expression of genes involved in oncogenesis, stemness, tumor growth, and progression, we next determined the effect of CDK7 inhibition on the expression of MYC, STAT3, and β-catenin." (PMID 32340192, 2020). "The JAK family of kinases are implicated in cancer through phosphorylation and activation of the STAT family of transcription factors, most notably STAT3 or STAT5, resulting in increased tumor cell proliferation and survival." (PMID 32234966, 2020). "An adiponectin-based short peptide named ADP 355 has high affinity with AdipoR1 and regulates canonical adiponectin signaling pathways (i.e., AMPK, Akt, STAT3, ERK1/2) to halt tumor growth." (PMID 33339340, 2020). "After that, the xenograft tumours RNA was extracted, the expression levels of HOST2 and let-7b was detected by qRT-PCR, and the expression of STAT3 was also detected by IHC staining." (PMID 32248842, 2020). "STAT3, and, in some cases, STAT5 and STAT6, affect the TME by promoting immunosuppressive TMEs and inhibiting anti-tumour immunity." (PMID 32414156, 2020). "We found that SH2D4A and PHB1 co-localize in mitochondria and treatment of tumor cells with the PHB ligand FL3 reduced SH2D4A, STAT3, and PHB1 protein levels but led to increased co-localization of PHB1 and pSTAT3-Ser727." (PMID 33257655, 2020). "Previous studies showed that Hsp90 overexpression was induced in MM cells by the activation of STAT3 and MAPK signaling, which was essential for tumor cell survival." (PMID 33102238, 2020).